RETN (resistin)
Diseases named in the same sentence as RETN in open-access papers (continued):
Sharing a sentence is not in itself a finding about the gene and the disease.
Obesity (continued). "Additionally, 11β-HSDH1 knockout mice were demonstrated to be resistant to hyperglycemia caused by obesity and stress, and they were shown to have low resistin and TNF-α levels and high PPARγ and uncoupling protein 2 (UCP2) levels compared with these in the control." (PMID 28386270, 2017). "Obesity was associated with higher adiponectin–resistin index value in sera (P < 0.0001) and decreased in subcutaneous adipose tissue (P < 0.001), but only adiponectin–resistin index measured in sera was significantly higher in obese with the metabolic syndrome (P = 0.04)." (PMID 29213336, 2017). "The diet-induced obesity in our wild-type mice, with mean body weights 20% above chow-fed controls, was not accompanied by changes in fasting glucose or insulin levels, but changes were seen in circulating cytokines associated with obesity: leptin, resistin and MCP-1." (PMID 27448965, 2016). "However, the role of resistin in obesity associated with fatty liver disease remains controversial." (PMID 25922835, 2015). "Thus, overproduction of obesity-related circulating resistin and associated low-grade inflammation may result in mild injury to pancreatic acini, increasing the risk and severity of AP." (PMID 25780448, 2015). "Thus, leptin and resistin may represent the principal mediators of the impact of obesity on the inflammatory markers involved in cardiovascular risk in T2D patients." (PMID 24736687, 2014). "Thus, human resistin may be linked from insulin resistance to inflammatory diseases such as obesity, type 2 diabetes, and atherosclerosis." (PMID 23634778, 2013). "Development of novel therapeutic procedures for obesity and obesity-associated diseases possibly could be achieved through an integral insight into leptin, resistin and visfatin, as well as insight into other adipokine functions and their links to inflammation." (PMID 23634778, 2013). "Adipokines (leptin, resistin and visfatin) could serve as a missing link in the causal relationship between psoriasis and comorbidities and may provide a biomarker for disease severity such as obesity and diabetes, risk of comorbidities and treatment success." (PMID 23634778, 2013). "Furthermore, we show that furin and MT1-MMP are significantly increased in obese patients and that furin is upregulated by the adipocytokine resistin in monocytes in vitro, supporting the concept that PCSKs contribute to obesity-associated chronic low-grade inflammation." (PMID 23936445, 2013). "Indeed, obesity is associated with elevated levels of cytokines whose systemic administration leads to impaired glucose homeostasis, such as TNFα and IL-6, which we show here to mediate the inflammatory induction of human resistin." (PMID 15578112, 2004). "At baseline, participants with obesity had significantly higher median resistin levels (6.43 ng/mL; interquartile range (IQR): 5.78-7.20) than participants without non-obesity (4.12 ng/mL; IQR: 3.45-4.26; p = 0.001)." (PMID 41602238, 2026). "The normal serum concentration of resistin is 7-22 ng/mL, but it is elevated in individuals with diabetes mellitus, atherosclerosis, inflammatory bowel disease, obesity, periodontitis, and several other systemic diseases." (PMID 41602238, 2026). "Comprehensive assessment of clinical periodontal parameters (PPD, CAL, FMBS, and FMPS) and salivary resistin level provided valuable insights into the relationship between obesity and periodontal health." (PMID 41602238, 2026). "Elevated AIF-1 levels correlate with inflammatory adipocytes and obesity, while reduced AIF-1 promotes weight loss through regulation of monoamine oxidase A and decreased leptin/resistin production." (PMID 41694567, 2026). "In obesity and diabetes, its inflammatory transformation results in increased secretion of leptin, resistin, and MCP-1/CCL2, along with diminished adiponectin secretion." (PMID 41596265, 2026).
Obesity (continued). "This cross-sectional study investigated the relationship between resistin, metabolic health, and obesity in an adult Mexican-American cohort (n = 1511) using multivariable linear regression analysis." (PMID 40362681, 2025). "Obesity has been shown to impair the synthesis and secretion of adipokines such as resistin and adiponectin in breast milk, both of which participate in feedback mechanisms regulating body weight and energy metabolism." (PMID 41301907, 2025). "The adipokines adiponectin, leptin, and resistin serve essential functions in the development of obesity and cardiovascular diseases as well as insulin resistance." (PMID 40013194, 2025). "The results of logistic regression analysis showed that obesity alone and type 2 diabetes with obesity were significantly associated with serum levels of TNF-α, IL-6, leptin, adiponectin, resistin, and ALR after adjusting for sex or age." (PMID 40095937, 2025). "As early as 2001, researchers discovered that adipocytes secrete resistin, which initially shed light on the link between obesity and insulin resistance." (PMID 40104135, 2025). "The pathophysiology of obesity has been connected to the inflammatory cytokine resistin, which is mostly generated by immune cells and adipose tissue." (PMID 41315571, 2025). "Since resistin is elevated in obesity, it is thought that, throughout the impact on TNF-α and IL-6, resistin can, to a certain extent, explain the association between obesity and the severity of psoriasis." (PMID 40277935, 2025). "It is noteworthy that an upregulation of resistin expression in gastrointestinal tract cells has been observed in gastrointestinal disorders, suggesting a potential link between obesity and cancer." (PMID 40002704, 2025). "A high-fat diet contributes to overweight and obesity by stimulating adipose tissue to secrete adipokines such as leptin, adiponectin, resistin, and visfatin." (PMID 40724666, 2025). "Beyond the well-established adipokines like adiponectin and leptin, resistin and visfatin have also come to the forefront in recent studies on obesity and cancer." (PMID 40040878, 2025). "Insulin resistance develops by deteriorating glucose homeostasis in mice treated with resistin, and administration of resistin antibodies in mice with dietary obesity reduces blood glucose levels and increases insulin sensitivity." (PMID 41417360, 2025). "FIP-fve reduced body weight, blood lipids, glucose, and crucial cytokines, including leptin and resistin, which are central to obesity-related insulin resistance and metabolic diseases." (PMID 40998975, 2025). "In contrast, resistin levels are elevated in obesity and have been shown to promote insulin resistance and the release of pro-inflammatory cytokines such as TNF-α and IL-6." (PMID 41155642, 2025). "Adipose tissue-derived hormones such as leptin, adiponectin, and resistin exert opposing effects on vascular homeostasis, influencing inflammation and oxidative stress in obesity and metabolic syndrome." (PMID 41155389, 2025). "Dysregulation of adiponectin, resistin, and leptin in obesity and AD establishes a pro-inflammatory and metabolically impaired environment in the brain." (PMID 41155642, 2025). "The release of adipokines such as chemerin, adiponectin, resistin, visfatin and C-reactive protein by macrophages and T-cells is the link between chronic systemic inflammation and obesity." (PMID 40003621, 2025). "Circulating levels of resistin positively correlate with obesity, promoting both inflammation and insulin resistance." (PMID 40699839, 2025). "In an obesity model, anthocyanins were able to reduce body mass and adipose tissue mass, positively impacting the secretion of the adipokines leptin and resistin, corroborating the improvement of inflammation by modulating the TLR4/AMPK pathways." (PMID 40195898, 2025).
Obesity (continued). "In contrast to the control group, circulating leptin and resistin levels were increased along with serum proinflammatory cytokines in obesity and diabetes." (PMID 40095937, 2025). "Obesity results in significant changes in the adipokine profile, creating a shift toward elevated levels of pro-inflammatory adipokines, such as leptin and resistin, and reduced levels of anti-inflammatory adipokines, such as adiponectin." (PMID 41158939, 2025). "In summary, resistin distinguishes itself as a plausible link between the metabolic complications of obesity and the pathogenesis of depression." (PMID 41375608, 2025). "Elevated resistin levels have been observed in obesity, type 2 diabetes, and cardiovascular disease, as well as in neurodegenerative disorders." (PMID 41155642, 2025). "Elevated levels of leptin, resistin, MCP-1, and ENA-78 are associated with various aspects of obesity-related complications." (PMID 39962072, 2025). "In individuals with obesity, adipose tissue—especially visceral fat—acts as an active endocrine organ that secretes various adipokines (e.g., leptin, resistin, adiponectin), pro-inflammatory cytokines (e.g., TNF-α, IL-6), and chemokines (e.g., MCP-1)." (PMID 41282294, 2025). "Although the role of resistin as a mediator of inflammation in obesity is well documented, further research is needed to elucidate its potential direct links with depression." (PMID 40507778, 2025). "The interaction term between TMAO and resistin was statistically significant (OR: 1.00, CI: 1.00–1.00, p = 0.010), indicating that their combined effect on obesity differs from their individual contributions." (PMID 40077669, 2025). "This relationship is highly relevant as it links resistin to inflammation and possibly to insulin resistance, making it of interest in studies related to metabolic disorders such as diabetes and obesity." (PMID 40491594, 2025). "The primary objective of this study is to characterize the relationship between circulating resistin levels and metabolic health and obesity in a Mexican-American cohort." (PMID 40362681, 2025). "The plot displays three distinct trends: at high resistin levels (+1 SD), the probability of obesity decreases as TMAO levels rise." (PMID 40077669, 2025). "Given the excessive accumulation of visceral adipose tissue observed in breast cancer, a clear link exists between resistin and obesity-induced carcinogenesis." (PMID 40040878, 2025). "In obesity, hypertrophic adipocytes release a spectrum of pro-inflammatory adipokines (e.g., leptin and resistin) and cytokines (e.g., IL-1β and IL-6), which are known to exacerbate autoimmune conditions." (PMID 40900762, 2025). "Studies have indicated that obesity is the primary determinant for increased expression of resistin in PCOS, and it is also considered a marker of promoting angiogenesis." (PMID 40385742, 2025). "In rodents, adipocytes predominantly secrete resistin, where it critically links obesity to insulin resistance and type 2 diabetes mellitus." (PMID 41347124, 2025). "Based on ROC analysis, resistin and sdLDL can be used as an indicator for the assessment of overweight and obesity." (PMID 41315571, 2025). "Obesity also enriches other proinflammatory adipokines (resistin, visfatin) in endometriotic lesions, driving local cytokine release." (PMID 40565786, 2025). "Mounting evidence from clinical studies has reported high serum resistin levels in patients with metabolically unhealthy obesity, hypertension, diabetes mellitus II, and renal and liver complications." (PMID 40699617, 2025). "By contrast, down-regulation of GIP and resistin and leptin had been reported to be beneficial for obesity or diabetes treatment." (PMID 41356823, 2025). "In obesity-driven HFpEF, resistin contributes to diastolic impairment by inducing myocardial stiffness and inflammation." (PMID 41347124, 2025).
Obesity (continued). "Consistent with this, our study observed significantly higher TMAO and resistin levels in participants with a family history of obesity, diabetes, or cardiovascular disease, reinforcing the potential hereditary influence on these biomarkers." (PMID 40077669, 2025). "The abundant presence of resistin is widely correlated with pathological conditions in the human body, e.g., obesity, insulin resistance, diabetes, and polycystic ovary syndrome." (PMID 40076482, 2025). "Obesity is also characterized by elevated levels of IR-inducing adipokines such as leptin, visfatin, and resistin." (PMID 41463398, 2025). "Adipokines, such as leptin and resistin, secreted by hypertrophic adipose tissue in obesity, enhance Th1 and Th17 polarization, contributing to pro-inflammatory cytokine production that disrupts microbial homeostasis." (PMID 39858932, 2025). "A meta-analysis published in 2019 concluded that there is a relationship between serum resistin levels and IR in patients with T2D and obesity; however, this conclusion was applicable only to subgroups of individuals with above-average resistin levels." (PMID 40283140, 2025). "In obesity, adipocytes exhibit upregulated expression of pro-inflammatory adipokines, such as leptin and resistin." (PMID 40893809, 2025). "Obesity induces profound alterations in adipose-derived signals, among which resistin and adiponectin emerge as antagonistic regulators of inflammation, metabolism, and neurodegeneration." (PMID 41155642, 2025). "In this review, we show, in an updated way, the link between obesity and changes in the signaling pathways of the adipokines leptin, adiponectin, resistin, visfatin, apelin, chemerin, omentin‐1, vaspin, and asprosin in male reproduction." (PMID 40195898, 2025). "Among these, leptin and resistin are the most extensively studied and are recognized as key signaling transducers linking obesity to psoriasis development." (PMID 40893809, 2025). "Lastly, our ROC analysis demonstrated that leptin had the highest diagnostic accuracy for predicting obesity in PCOS (AUC=0.85, 95% CI: 0.79-0.91, p<0.001), followed by adiponectin (AUC=0.77, p=0.004) and resistin (AUC=0.73, p=0.015)." (PMID 40792318, 2025). "As a component of the dysregulated adipokine milieu in obesity, resistin contributes to an imbalance favoring proinflammatory mediators over protective adipokines such as adiponectin." (PMID 41347124, 2025). "In patients with depression comorbid with metabolic complications (e.g., obesity or type two diabetes mellitus), high resistin levels worsen glycaemic control and inflammation." (PMID 41375608, 2025). "The interaction between TMAO and resistin suggests a collective influence on obesity-related insulin resistance and cardiovascular complications, reinforcing their importance in metabolic risk assessment." (PMID 40077669, 2025). "Both TMAO and resistin were identified as significant predictors of obesity, with a statistically significant interaction between them, suggesting a more complex relationship beyond their individual effects." (PMID 40077669, 2025). "The logistic regression model evaluated the predictive value of TMAO, resistin, and their interaction in relation to obesity, explaining 32.1% of the variance (Nagelkerke R2 = 0.321)." (PMID 40077669, 2025). "Obesity alters the secretion of adipose-derived hormones such as leptin, adiponectin, and resistin, and these imbalances have profound effects on metabolic homeostasis and cardiovascular health." (PMID 41282294, 2025). "The content of saturated fatty acids, which are present in large amounts in red meat, is a factor that increases resistin levels, especially in obesity." (PMID 39796247, 2025). "Current clinical evidence suggests that resistin levels tend to increase in the presence of metabolic disorders such as obesity, metabolic syndrome, insulin resistance (IR), and type 2 diabetes (T2D)." (PMID 40283140, 2025).
Obesity (continued). "At average resistin levels (mean), a positive association is observed between TMAO and obesity, where increasing TMAO levels correspond to a higher obesity risk." (PMID 40077669, 2025). "Some relationship between circulating concentrations of resistin and insulin resistance has been reported in humans with type 2 diabetes mellitus and obesity." (PMID 41441039, 2025). "For example, in knee synovial fluid samples of patients with obesity and OA, levels of adiponectin, leptin, resistin, and visfatin were found to be elevated." (PMID 39152660, 2025). "Obesity exacerbates inflammation through immune cell activation in adipose tissue and the release of proinflammatory adipokines, such as leptin, resistin, and IL-18, which enhance autoimmune responses and insulin resistance." (PMID 40277935, 2025). "In contrast, at low resistin levels (−1 SD), the probability of obesity rises sharply with increasing TMAO levels." (PMID 40077669, 2025). "Resistin levels can be increased in obesity and other inflammatory diseases, but the correlation between the increase in BMI and resistin concentration is small." (PMID 40095687, 2025). "Particularly, leptin, resistin, and PCSK9 demonstrated obvious decreases compared to the Fat only group, indicating FIP-fve’s ability to ameliorate obesity-associated metabolic and inflammatory alterations." (PMID 40998975, 2025). "In obesity, the dysregulated secretion of adipokines such as leptin, adiponectin, resistin, and chemerin from AT affects periodontal tissues through multiple pathways." (PMID 41246338, 2025). "Key factors in obesity-induced inflammation include several adipokines (e.g., leptin, resistin, adiponectin), with their serum levels and corresponding receptor expression in adipose tissue serving as indicators of the obesity–psoriasis connection." (PMID 40893809, 2025). "Leptin and resistin, which are elevated in obesity, further aggravate plaque instability by inducing reactive oxygen species (ROS), smooth muscle cell proliferation, and extracellular matrix remodeling." (PMID 41282294, 2025). "People with obesity had higher leptin concentrations (p=0.03, and p<0.01), lower adiponectin/leptin (p=0.03 and p<0.01), and higher leptin/resistin ratios (p=0.09 and p<0.01) in both AT and serum respectively." (PMID 40352457, 2025). "These alterations in leptin, adiponectin, and resistin contribute to improved metabolic profiles and reduced chronic inflammation related to obesity." (PMID 40733199, 2025). "Adipokine production, i.e., leptin, adiponectin, resistin and visfatin, is a key mechanism through which obesity leads to a pro‐inflammatory state." (PMID 39152660, 2025). "Our results therefore show not only a reduction in the development of obesity and inflammation but also an increase in both leptin and resistin levels, and leptin resistance when using KSK-94 in animals with unlimited access to tasty food." (PMID 39065709, 2024). "The findings of this study that show abundant resistin expression in mature adipocytes corroborate and complement existing knowledge about the mechanisms involved in insulin resistance during obesity, indicating the strong involvement of oxidative stress." (PMID 39765824, 2024). "Whereas Cross-fit® + spinach-derived thylakoid decreased the proinflammatory leptin and resistin and increased the anti-inflammatory adiponectin and omentin in males with obesity, suggesting a reduction of inflammation, a feature of BF accumulation." (PMID 38337640, 2024). "Other studies reported a positive correlation between resistin and leptin serum levels in metabolic syndrome, obesity, and diabetes mellitus type 2." (PMID 39062875, 2024). "The last of the colostral molecules evaluated in this study was resistin, an important player in diabetes and obesity." (PMID 38612666, 2024). "As for the lipid profile, in our study, changes in resistin concentrations correlated positively with ApoB concentrations in subjects with obesity." (PMID 39519480, 2024).